BDNF (brain derived neurotrophic factor)
Diseases named in the same sentence as BDNF in open-access papers (continued):
Sharing a sentence is not in itself a finding about the gene and the disease.
Stroke (continued). "For example, polymorphisms of the apolipoprotein E (APOE) and brain-derived neurotrophic factor (BDNF) genes may influence outcome after stroke." (PMID 23750149, 2013). "In addition, the BDNF met allele frequency of this stroke patients were similar to that from a population based study of a Korean elderly (47%)." (PMID 23240009, 2012). "This study aimed to investigate whether BDNF val66met polymorphism and promoter methylation status were associated with outcomes at two weeks and one year after stroke." (PMID 23240009, 2012). "However, the miR-10b-5p/BDNF axis may represent a biologically plausible pathway associated with post-stroke epileptogenesis and impaired post-ischemic recovery." (PMID 41789165, 2026). "There has been little support for dopamine agonists, such as bromocriptine and levodopa in the treatment of post-stroke aphasia; however, future research taking genetics into consideration, specifically BDNF polymorphisms may assist with matching patients who may be more or less responsive." (PMID 40808812, 2025). "The apparent discrepancy between the limited available acute and chronic studies’ findings may be due to the fact that effects of the Met allele are subtle relative to the high variability in early stroke recovery, characterized by a reduction of 18%–30% in activity-dependent BDNF secretion." (PMID 40658687, 2025). "Although it seems reasonable to hypothesize that HIIT-induced BDNF release may be of help in the recovery of stroke patients, the alterations caused by ischemic events may modify the physiological response of the affected area not being comparable to that observed in healthy individuals." (PMID 38610750, 2024). "So, BDNF may be a potential biomarker for stroke risk prediction in patients unable to receive TCD." (PMID 36774398, 2023). "Therefore, the BDNF gene may show a significant association with aphasia recovery after stroke, with the Met allele of the gene linked to poorer language recovery." (PMID 34367374, 2021). "Therefore, although they did not directly explore the relationship between BDNF levels and PSD in patients with stroke, it was indicated that decreased expression of BDNF levels might be associated with the development of PSD." (PMID 34141514, 2021). "However, the exact role of BDNF polymorphisms in language performance and recovery in stroke may require further investigation." (PMID 34367374, 2021). "Moreover, neurotrophic factors, such as brain-derived neurotrophic factor and basic fibroblast growth factor, significantly decrease in both the cortex and striatum in old mice as compared with young mice after stroke, leading to impaired support to the neurons at risk of death from ischemia." (PMID 33958997, 2021). "Employing an assumption that BDNF Val66Met polymorphism influences the severity and recovery of aphasia, identifying specific alleles of BDNF as a predictor for aphasia severity and recovery may be the next step targeting selective therapeutic strategies in stroke patients." (PMID 34367374, 2021). "Moreover, the results may provide a base for our future study regarding the regulation of HIF-1α on the BDNF/TrkB/CREB pathway in the biochemical processes underlying post-stroke synaptic plasticity." (PMID 32670026, 2020). "Additionally, the results may provide a base for our future study regarding the regulation of HIF-1α on the BDNF/TrkB/CREB pathway in the biochemical processes underlying post-stroke synaptic plasticity." (PMID 32670026, 2020). "The reverse association between ALA and BDNF detected in our study may reflect diverse metabolic processes in humans compared to animal models or may result from the affected metabolism of BDNF during stroke." (PMID 33343231, 2020).
Stroke (continued). "Our results showed that the methylation level of the CpG site included in the BDNF rs6265 polymorphism was significantly different between the GG, GA and AA alleles (p < 0.001), indicating an association between genotypes and methylation in patients with stroke." (PMID 33182716, 2020). "Thus, this study has suggested that the stability of BDNF and proBDNF and their linked proteins may play a pivotal role in stroke recovery." (PMID 29997355, 2018). "Therefore, besides the complexity of events related to IGF-1 activity, even when associated with BDNF, for many emerging myokines a possible role as biomarkers in stroke yet needs confirmation in clinical studies, despite the encouraging evidence coming from in vitro or animal studies." (PMID 28373915, 2017). "Overall, the data led us to suspect a link between cardiovascular status and serum BDNF levels in stroke patients and in turn to investigate the relationship between the European cardiovascular risk score at admission (a high score meaning a high risk) and serum BDNF levels." (PMID 26469350, 2015). "While this and other BDNF variants have received much attention in recent years in relation to a variety of diseases and outcome measures such as neuropsychiatric disorders, Alzheimer's, multiple sclerosis, and Parkinson's, clinical studies in stroke are limited." (PMID 25470006, 2014). "Furthermore, given that the BDNF met allele is associated with reduced activity-dependent secretion of BDNF, functional deficiency at the chronic phase of stroke might also be associated with less BDNF secretion." (PMID 23240009, 2012). "The BDNF val66met polymorphism has been associated with poor outcome after intracerebral bleeding and it has been speculated that it might influence recovery after stroke." (PMID 23152767, 2012). "In terms of adult neurogenesis and stroke-induced neurogenesis, brain-derived neurotrophic factor (BDNF) is the most extensively researched neurotrophic factor." (PMID 41601967, 2026). "Consistently, research indicates that patients across both the acute and chronic phases of stroke present with markedly reduced serum and plasma BDNF levels compared to healthy individuals." (PMID 41598337, 2026). "The expression of both NGF/TrkA and BDNF/TrkB increases post-stroke as part of a self-rescue mechanism." (PMID 40536921, 2026). "BDNF, a key regulator of post-stroke recovery and epileptogenesis, was identified as a primary target of miR-10b-5p." (PMID 41789165, 2026). "In stroke rehabilitation, BDNF is recognized as a fundamental molecular driver of neuroplasticity, facilitating the neural adaptations required for motor and functional recovery." (PMID 41598337, 2026). "We evaluated the BDNF expression at day 21 after stroke of MPP-B@MM group and found significant increment." (PMID 41328343, 2026). "Systematic reviews and meta-analyses in stroke survivors show that both single sessions and programs of high-intensity aerobic exercise markedly increase circulating BDNF concentrations, thereby creating a permissive environment for neuroplasticity." (PMID 41598337, 2026). "The pooled results show that acupuncture significantly promotes neuroregeneration and tissue repair after stroke, as indicated by BDNF: I2 = 40.1%; SMD: 3.74, 95% CI [3.21, 4.27], p = 0.124." (PMID 40842100, 2025). "BDNF is a central mediator of exercise-induced neuroprotection in several neurological disorders including AD, PD, and stroke recovery." (PMID 40362507, 2025). "After stroke, decreased levels of BDNF affect the regulation of neuroplasticity and the potential for self-repair." (PMID 40948655, 2025). "Cardiovascular exercise (CE) has been recommended for stroke rehabilitation, partly due to its potential to induce neural adaptations, including upregulation of BDNF." (PMID 40462267, 2025). "Stroke impairs BDNF signaling, disrupting neurogenesis and axonal regeneration, which increases the risk of developing PSD." (PMID 40529498, 2025).
Stroke (continued). "The distinct expression of BDNF in neurons and astrocytes suggests their involvement in different cellular processes under stroke conditions." (PMID 39889003, 2025). "For instance, the analogs of brain-derived neurotrophic factors (BDNF) have been shown to promote angiogenesis and neuronal repair in stroke models." (PMID 40428061, 2025). "In other words, NIBS is more likely to improve language performance through cortical plasticity in post-stroke individuals who carry the typical BDNF genotype because they express higher levels of BDNF." (PMID 40808812, 2025). "BDNF infusion immediately after stroke has been shown to reduce brain tissue damage, improve LTP, and promote functional recovery." (PMID 40969839, 2025). "Oxidative stress and inflammation are associated with the late phase of stroke, leading to the activation of CASP8 and increased CASP8 activity levels, whereas BDNF levels remain low73,74." (PMID 40133606, 2025). "PSD affects stroke outcomes through multiple mechanisms, including excitotoxicity, increased levels of pro-inflammatory cytokines, and downregulation of brain-derived neurotrophic factor (BDNF), a key mediator of brain repair." (PMID 40144654, 2025). "New knowledge is to be gained by examining post-stroke phases of recovery with improved granularity in the context of BDNF and communication." (PMID 40658687, 2025). "Western blotting of the GluN3A KO brain in the MEM group showed a significant increase in BDNF expression, after 1.5 months of continued post-stroke MEM treatment." (PMID 41369361, 2025). "The administration of BDNF analogs increases the vascular density and neuronal activity in the affected brain regions post-stroke, thereby facilitating neurovascular unit remodeling and accelerating the functional recovery." (PMID 40428061, 2025). "Within-group and between-group differences of BDNF and plasma cholinergic markers in patients with minor stroke at the start of the intervention and after 3 months." (PMID 40520612, 2025). "A significant post-stroke reduction in BDNF levels was observed (p < 0.02, 25% reduction) when all samples (n = 56, Ln data) were compared between baseline versus 3-month follow-up." (PMID 40520612, 2025). "Patients with AIS exhibit significantly lower serum levels of BDNF compared to healthy individuals, with stroke severity inversely related to BDNF levels." (PMID 41280373, 2025). "In the 5xFAD mouse brain, the BDNF expression in MEM-treated brains significantly increased after stroke." (PMID 41369361, 2025). "Results on BDNF levels in stroke patients are vary, mainly being affected by the time since stroke event (within 10 days or longer), matrix (plasma or serum) or method used." (PMID 41447407, 2025). "This study presents an exploratory analysis aimed at gaining insight into the potential interrelationships between stroke, brain-derived neurotrophic factor (BDNF), and the modulation of key components of the cholinergic system." (PMID 40520612, 2025). "While increases in BDNF following cognitive training have been demonstrated in other populations, evidence in stroke survivors remains scarce, with studies to date reporting predominantly negative findings." (PMID 40283415, 2025). "Stroke and Traumatic Brain Injury: Systemic delivery of neurotrophic factor-loaded EVs (e.g., BDNF, NGF, miR-124) via intravenous or intranasal routes significantly improved neurological recovery and reduced infarct volume in rodent stroke models." (PMID 41155971, 2025). "Future research should validate these results in larger cohorts, explore BDNF supplementation strategies in diabetic stroke models, and investigate the clinical utility of BDNF-based interventions within thrombolysis protocols." (PMID 41280373, 2025). "We conclude that SMS-guided exercise training improves post-stroke walking performance (6MWT) which attenuates the decline in BDNF levels." (PMID 40520612, 2025).
Stroke (continued). "This study is the largest trial investigating the effects of CE training on BDNF levels in individuals recovering from a stroke and the first trial exploring the effects in early subacute stages." (PMID 40462267, 2025). "In a discussion of neuroplasticity and cognitive recovery after stroke, brain-derived neurotrophic factor (BDNF) emerges as a critical molecular player." (PMID 40492169, 2025). "Exercise intervention reduces post-stroke depression-like behavior by activating SIRT1/BDNF/mTORC1 signaling pathway and reducing neuroinflammation." (PMID 40071363, 2025). "In a mouse stroke model, tDCS increased peri-infarct BDNF levels and spike firing, with corresponding increases in circulating BDNF that predicted functional recovery." (PMID 41440017, 2025). "These dual mechanisms—suppression of NLRP3-driven neuroinflammation and enhancement of BDNF-mediated neuroplasticity—highlight the critical role of aerobic exercise in post-stroke rehabilitation." (PMID 40256392, 2025). "This study aimed to investigate the influence of the BDNF genotype on aphasia recovery following a stroke." (PMID 40658687, 2025). "TMS improves cognitive function in post-stroke patients, changes in brain-derived neurotrophic factor concentrations under the influence of TMS, and also enhances connectivity in the bilateral DLPFC brain area network." (PMID 40948655, 2025). "We report that BDNF levels were significantly reduced post-stroke until 3 months compared to the baseline but remain within the quantitative range." (PMID 40520612, 2025). "A prospective cohort study identified fibrinogen as the primary predictive marker for PSD in men at 3 months post-stroke, while free T3, BDNF, and magnesium were key indicators in women." (PMID 40255888, 2025). "Another study demonstrated that intranasally delivered mesenchymal stem cells overexpressing BDNF also yielded superior, albeit temporary, functional recovery in a neonatal stroke model." (PMID 41304786, 2025). "The authors concluded that the serum BDNF level has a minimal predictive clinical effect on the motor status in early stroke rehabilitation." (PMID 40141452, 2025). "A decline in BDNF levels was observed in accordance with the severity of AIS with the least level being in severe stroke (NIHSS ≥ 16)." (PMID 41280373, 2025). "Among stroke survivors, aerobic activity plus task oriented physical therapy elevated serum BDNF levels up to 2-fold compared to physical therapy alone." (PMID 40362507, 2025). "Prior studies have shown that cAMP/cGMP-mediated signals can activate downstream transcription factor cAMP response element-binding protein (CREB; Lee, 2015) and further induce CREB-regulated gene expression of BDNF to promote recovery after stroke." (PMID 40692577, 2025). "Further research using various methods, including by other research groups, is necessary to confirm the neurorehabilitative potential of hypercapnic hypoxia and to determine the presence of a causal link between BDNF/VEGF and improved post-stroke recovery." (PMID 41465442, 2025). "BDNF also reiterates the potential for a possible additive therapeutic effect when re-engaging exercise and BDNF in a continuum of recovery post-stroke." (PMID 40362507, 2025). "In another context, psilocybin, administered post-stroke, improves motor recovery, reduces neuroinflammation, and promotes neuroplasticity by activating the TrkB receptor and increasing levels of BDNF, MAP2, and synaptophysin." (PMID 41369360, 2025). "By increasing BDNF levels, they protect brain tissue, improve post-stroke muscle spasticity, enhance motor function and activities of daily living—key aspects of rehabilitation—playing a vital role in facilitating cognitive recovery." (PMID 40959502, 2025). "Beyond its biological action, recent studies have pointed to BDNF as a prognostic biomarker in stroke, linking high serum BDNF concentrations in the acute phase of stroke with a lower incidence of subsequent severe disability and mortality." (PMID 41155363, 2025).
Stroke (continued). "The BDNF genotype is being increasingly investigated as potential valuable biomarker in post-stroke recovery across domains of function." (PMID 40658687, 2025). "In stroke mice injected with M-EV, BDNF expression was significantly higher, promoting the recovery of damaged neurons." (PMID 40873771, 2025). "In preclinical studies using a rat stroke model, physical exercise improved functional recovery by reducing neuroinflammation and increasing BDNF expression around the lesions." (PMID 40361157, 2025). "Recent studies have indicated that 5HT2A agonists, such as dimethyltryptamine, given before middle cerebral artery occlusion (MCAo), improve staircase behavior, increased BDNF expression, and reduce brain infarction in stroke rats." (PMID 39379834, 2024). "This is supported by previous studies indicating that BDNF enhances synaptophysin expression, thus contributing to synaptic plasticity and recovery post-stroke." (PMID 39519132, 2024). "In general, patients with CHF and stroke have lower BDNF levels, whereas thosewith unstable angina and recent MI have higher BDNF levels." (PMID 39077334, 2024). "This composite was then applied epi-cortically, directly above the stroke lesion, in a rat model of stroke, allowing BDNF to diffuse into the brain, leading to enhanced behavioral recovery and increased synaptic plasticity in the contralesional hemisphere." (PMID 39057499, 2024). "This study aimed to assess rTMS’s effect on post-stroke endogenous neuroplasticity by dosing plasma miRs 17~92, Netrin-1, Sema3A, and BDNF." (PMID 38540283, 2024). "The level of brain‐derived neurotrophic factor (BDNF) in the serum was shown to be significantly reduced in patients in the acute stroke stage, and the severity of stroke was negatively correlated with BDNF levels." (PMID 38727249, 2024). "Research to date has primarily focused on the individual impacts of lipid profiles and BDNF in stroke." (PMID 38397057, 2024). "HF-rTMS intervention should be individualized based on functional corticospinal tract status and brain-derived neurotrophic factor genotype to improve the upper extremity motor of patients with stroke." (PMID 39268062, 2024). "BDNF has shown effectiveness in treating CNS disorders, including stroke, by various mechanisms, and it holds significant potential for repairing brain damage." (PMID 39095888, 2024). "According BDNF levels decrease immediately after stroke, however, additional therapy and exercise can further increase these levels again and positively influence the repair mechanisms." (PMID 39224579, 2024). "Many studies reported decreased BDNF level after stroke, and treatments or drugs that boost BDNF level have been proven to contribute to rehabilitation after stroke." (PMID 39090706, 2024). "Specifically, the administration of Semax increased brain-derived neurotrophic factor (BDNF) plasma levels, accelerated functional recovery, and enhanced motor performance in post-stroke patients." (PMID 38534749, 2024). "Collectively, these results suggest that inhibition of let-7i in experimental models of stroke promotes neuroprotection by increasing BDNF release, a process mediated by Pgrmc1." (PMID 38469139, 2024). "Nevertheless, during the acute phase of stroke, an inverse correlation exists between stroke severity and BDNF levels." (PMID 38169754, 2024). "HIIT protocols in patients with stroke increase neuroplasticity biomarkers such as BDNF, VEGF and lactate." (PMID 38610750, 2024). "As a result, these findings suggest that BDNF can be used as a biomarker for assessing stroke prognosis and as a therapeutic target for improving stroke outcomes." (PMID 38397057, 2024). "Circulating levels of BDNF in stroke are poorly documented, and the available data have all been obtained in humans." (PMID 39568824, 2024).